SOX2 (SRY-box transcription factor 2)
Diseases named in the same sentence as SOX2 in open-access papers (continued):
Sharing a sentence is not in itself a finding about the gene and the disease.
glioblastoma (continued). "Further regulators of CD49f expression include positive regulation by Oct4 and Sox2 in mesenchymal stem/stromal cells and negative regulation by KLF9 in glioblastoma stem cells, which is important for repressing CD49f expression and glioblastoma stemness." (PMID 36246104, 2022). "Here, we demonstrate that U87 glioblastoma 3D neurospheres culture conditions can partially recapitulate the CSC chemoresistance and invasive molecular signature by increasing PROM1, SOX2, and NANOG expression." (PMID 36497426, 2022). "The GSC markers (SOX2, OCT4, CD9, CD133, and nestin) indicate the differentiation of glioblastoma cells into GSCs." (PMID 35054779, 2022). "There is a direct correlation between the expression of SOX2 and TWIST1 in glioblastoma cells, suggesting their interaction to maintain stemness and EMT ability." (PMID 36553636, 2022). "The expression of four pluripotency-related genes was investigated (OCT4, NANOG, SOX2, and CARM1) in the most malignant primary human brain tumor, glioblastoma (GBM)." (PMID 35274101, 2022). "LDA analysis revealed multiple distinct recurrent cellular neighborhoods in adult glioblastoma, including a neighborhood that combined CD39, CD73, SOX2, and CD163 expressing cells (Topic #11)." (PMID 35973991, 2022). "Unfortunately, the SOX2OT–SOX2 interaction results in increasing the SOX2 level, leading to higher TMZ resistance of glioblastoma." (PMID 36012529, 2022). "The recent evidence suggested that delivering both miR-124 and miR-145 into glioblastoma cells via MSCs-derived exosomes increased Sox2 and OCT4 expression to hamper the proliferation of glioblastoma cells." (PMID 35096289, 2021). "Cells expressing proteins including SOX2, OCT4, pSTAT3, KLF4, NANOG, and SALL4 were identified as CSCs in Glioblastoma multiforme (GBM)." (PMID 33799834, 2021). "Together, these findings confirm that DYRK1A negatively regulates SOX2 expression via CDK5 pathway and thus is necessary for the differentiation commitment of glioblastoma stem cells." (PMID 33924599, 2021). "In line with its neural and stem cell renewal function, SALL2, combined with SOX2, POU3F2, and OLIG2 transcription factors, promotes the de-differentiation of glioblastoma cells into stem-like tumor propagating cells." (PMID 33692826, 2021). "To validate the DYRK1A-CDK5-SOX2 axis in glioblastoma cells, we analysed how DYRK1A inhibition changes SOX2 expression in CDK5-depleted cells." (PMID 33924599, 2021). "A recent study identified four transcription factors (SOX2, SALL2, OLIG2, and POU3F2) as the minimal core sufficient to reprogram differentiated glioblastoma (GBM) cells into stem-like cells." (PMID 34282187, 2021). "A subset of patient glioblastoma samples with high SFRP2 and low SOX2 expression was particularly enriched with mesenchymal subtype samples." (PMID 34021259, 2021). "A role in intratumoral heterogeneity is suggested by the spatial distribution or SOX2 and SFRP2 expressing cells in glioblastoma tumors." (PMID 34021259, 2021). "In glioblastoma stem cells (GSCs), METTL3 promotes mRNA methylation, enhances the stability and expression of SRY-box transcription factor 2 (SOX2), and promotes maintenance and radio-resistance." (PMID 34105069, 2021). "In summary, SOX2-overexpression mirrored the SFRP2-overexpression phenotype and a subgroup of glioblastomas with high SFRP2 and low SOX2 expression was enriched with mesenchymal subtype tumors." (PMID 34021259, 2021). "On the other side, knockout of SOX2 attenuates the fitness and self-renewal of GSC and impairs glioblastoma invasiveness and tumorigenicity." (PMID 33924599, 2021). "One of the possible reasons is the use of serum-free neurobasal medium in all the recent studies of 3D cell culture systems for glioblastoma, which enriches OPC-like phenotype upon enhanced Olig2 and Sox2 which are the markers for the same." (PMID 34489494, 2021).
glioblastoma (continued). "Ablation of CD70 in glioblastoma cells reduced genes correlated with tumor epithelial mesenchymal transition (EMT), such as SOX-2 and CD44, and inhibited the migration and growth of the tumor." (PMID 32429463, 2020). "Recently, the putative markers frequently being used to identify and/or isolate glioblastoma stem cells (GSCs) include: CD133, CD44, CD15, CD70 (CD27 L), S100A4, ALDH1A3, Nanog, OCT-4, SOX-2, and Nestin." (PMID 32429463, 2020). "Other embryonic stem cell factors such as OCT4, SOX2, MYC, and KLF4 are also found differentially expressed in glioblastoma and normal neural stem cells." (PMID 33182324, 2020). "Nevertheless, the oncogenic role of METTL3 was shown in another study, where METTL3-mediated m6A modification enhanced SOX2 mRNA stability, METTL3 knockdown decreased glioblastoma stem cell growth in a SOX2-dependent manner." (PMID 32709063, 2020). "In glioblastoma, FOXM1 has been shown to promote stemness by modulating SOX2 expression in vitro and in vivo, and in neuroblastoma cells, FOXM1 was shown to directly activate SOX2 expression." (PMID 32210076, 2020). "They showed that a HIF-2α-SOX-2/OCT-4-Mena axis is intensely activated in hypoxia and significantly increased the migratory potential of the glioblastoma cells." (PMID 32429463, 2020). "In glioblastoma multiforme (GBM), a core set of neuro-developmental TFs (POU3F2, SOX2, SALL2, OLIG2) has been identified that was sufficient to reprogram differentiated glioblastoma cells to CSCs." (PMID 33297508, 2020). "In glioblastoma (GBM), suppression of SOX2 in GSCs resulted in cell cycle arrest and markedly reduced their abilities of cell growth, migration, invasion, and tumorigenicity." (PMID 32754274, 2020). "In a study conducted on glioblastoma stem cells (GSCs), NOTCH1, SOX2, SALL2, POU3F and OLIG2 blocked differentiation in GSCs, confirming the observations made in GBM by Suvà and colleagues." (PMID 32634370, 2020). "The glioblastoma cell lines A172, U251, and LN229 were found to express stem cell markers CD133, Oct4, Nanog, and Sox2." (PMID 32682409, 2020). "For example, amplification of the SOX2 gene has been reported in human squamous cell carcinomas (SCC) of the lung and esophagus, small-cell lung cancer (SCLC) and glioblastoma." (PMID 31041783, 2019). "Several studies have shown the presence of a core embryonic stem cell-like stemness signature in glioblastomas consisting of NANOG, OCT4, and SOX2." (PMID 30353164, 2019). "In glioblastoma, anti-miR-182 expression results in increased expression of biomarkers for proliferation and stem cell biomarkers (e.g., CCNB1, CD44, Sox2, and Nestin)." (PMID 31007608, 2019). "The oncogenic role of Notch1 can also be due to the infection of human cytomegalovirus, which upregulates Notch1, ATF5 (an anti-apoptotic protein already highly expressed in Glioblastoma), and stem cell markers CD133, nestin, SOX2, OCT4, KLF4, and BMI-1." (PMID 30832246, 2019). "miR-145 bound to the SOX2 mRNA 3′-untranslated region (3′UTR) and affected the anticancer response of isorhapontigenin in glioblastoma." (PMID 30742067, 2019). "A subset of only four of them–SOX2, OLIG2, POU3F2, and SALL2–was sufficient to fully reprogram differentiated cells into glioblastoma stem-like cells." (PMID 29773872, 2018). "Glioblastoma stem cells rely on multiple key stemness-related proteins such as Nestin, CD133, SOX2, Olig2, BMI1, and ZEB138,39." (PMID 30022047, 2018). "A more recent study has shown that the tumor-propagating potential of glioblastoma cells can be enhanced by increasing the expression of a set of transcription factors normally involved in neuronal development, including POU3F2, SOX2, SALL2 and OLIG2." (PMID 29609590, 2018). "In the present study, we demonstrated that PTUPB also inhibits the expression of stemness maerkers BMI1, SOX2 and the activation of ERK1/2 in glioblastoma cell lines." (PMID 29152086, 2017).
glioblastoma (continued). "Double-immunofluorescence stainings in glioblastomas revealed co-expression of JAM-A with CD133, SOX2, nestin, and GFAP in tumor cells as well as some co-expression with the microglial/macrophage marker IBA-1." (PMID 28677106, 2017). "We herein found that expression of SOX2 was decreased, whereas expression of OLIG2 and POU3F2 were increased in both rat and human glioblastoma cell lines under sphere culture conditions." (PMID 28717188, 2017). "To further study this putative correlation between SOX2 and SOX1, we moved to clinical biopsies, analyzing the expression of those transcription factors in the Donostia Hospital cohort of human glioblastoma samples." (PMID 28425506, 2017). "SOX2+ HIF-1α+ RNApII-S2P-/low cells were found, albeit at a low frequency, in glioblastoma tissues around large ischemic necroses." (PMID 26799577, 2016). "To discuss the roles of HIF-2α in the stemness and quiescence of glioblastoma cells within the peri-necrotic niche, which is the focus of our study, we compared the localization of HIF-2α+ cells with that of SOX2+ HIF-1α+ RNApII-S2P-/low cells." (PMID 26799577, 2016). "We found that metformin down-regulated SOX2 expression in TMZ-resistant glioblastoma cells, reduced the formation of neurospheres by glioblastoma cells, and inhibited tumor growth in vivo." (PMID 27791206, 2016). "POU3F2 and other neuro-developmental transcription factors (SOX2, SALL2 and OLIG2) coordinate to play essential roles in the progression of glioblastoma." (PMID 27271588, 2016). "These facts together with its prominent role in the regulation of GSCs suggest that SOX2 might be a key responsible factor for resistance to current chemotherapy and postulate that targeting its activity may offer a novel, attractive therapeutic approach to treat glioblastoma patients." (PMID 27822457, 2016). "First, the expression of SOX2, NANOG, HIF-1α, and RNApII-S2P in glioblastoma tissue was investigated by single-color immunohistochemistry." (PMID 26799577, 2016). "In this study, FASN was highly detected in the cytoplasm of human glioblastoma cells, and FASN was frequently co-localized with Sox2, a marker of GSC." (PMID 26808816, 2016). "We have recently observed that several oncogenic SOX2 functions are mediated by SOX9, another member of the SOX family, which also carries out important functions in GSC regulation and glioblastoma." (PMID 27822457, 2016). "Incubation of glioblastoma stem cells with CTGF protein increased the expression of GFAP and a decrease of Sox2 proteins, indicating an increase in the differentiation rate of these cells." (PMID 26241738, 2015). "Our research indicated that either suppressing miR-381 or enhancing NEFL expression sensitizes glioblastoma cells to TMZ by inhibiting stemness factors (ALDH1, CD44, CKIT, KLF4, Nanog, Nestin, and SOX2)." (PMID 25605243, 2015). "This study further investigated the effects of OPN overexpression on transcriptions of key stemness transcription factors SOX2, OCT4, and Nanog, in which transcription repression by OPN silencing has been demonstrated in stem-like glioblastoma cells in vivo." (PMID 26106421, 2015). "The CD133+ glioblastoma cell induced-tumor tissue expressed significantly higher levels of Oct4, Sox2, PCNA, EGFR, Ang2, MMP2 and MMP9 proteins compared with the CD133− glioblastoma cell induced-tumor tissue (P<0.05)." (PMID 23251243, 2013). "Our data indicate that critical stem cell regulators, such as SOX2 and OLIG2, are induced by the ZEB1-miR-200 feedback loop in glioblastoma." (PMID 23818228, 2013). "Similar to the glioblastoma cells, transduced DAOY cells were cultured in the presence of increasing concentrations of Dox to induce SOX2 expression." (PMID 22937156, 2012). "Glioblastoma cells forming aggregates, as well as undifferentiated GFAP+NNP, co-expressed SOX-2, Nestin, Beta III-tubulin, MAP2, GFAP, Vimentin, Fibronectin and CD44, when cultured under serum-starvation media." (PMID 19216795, 2009).
glioblastoma (continued). "ICI non-responders were enriched in glioblastoma stem cells marked by SOX2 and PTPRZ1 and in cells marked by the IL-6 effector p-STAT3 in both pre- and post-ICI samples compared to ICI responders." (PMID 40161763, 2025). "For example, glioblastoma stem cells express the methylase LSD1, which dynamically shuts down MYC, SOX2 and other stemness genes, allowing the cells to enter a ‘dormant state’ during drug treatment and reactivate the tumourigenic program after drug discontinuation." (PMID 40665579, 2025). "Fascinatingly, TRIM26 was found to stabilize SOX2 protein and enhance its oncogenic activity in glioblastoma via its C-terminal PRYSPRY domain without engaging its Ring domain and E3 ligase activity." (PMID 38260302, 2024). "In keeping with this conclusion, PTEN‐deficient human NSC undergo malignant transformation when injected into the brain of immunocompromised NOD/SCID mice, giving rise to tumours expressing SOX2, GFAP, NESTIN, TUJ1, MAP2, and CD133, similarly to human glioblastoma." (PMID 39148319, 2024). "Furthermore, PLD can repress glioblastoma cell migration and invasiveness by inhibiting the EGFR/AKT/ERK1/2/STAT3/SOX2/Snail signaling pathway." (PMID 39408901, 2024). "The high recurrence and therapy resistance of human glioblastoma may be attributed to the presence of GSCs in GBM, which often accompany high expression levels of the transcription factor SOX2." (PMID 40342640, 2024). "Furthermore, glioblastoma stem cells (GSCs) were assessed for the expression levels of OCT4 and SOX2, and Pearson correlation analysis was performed." (PMID 39588508, 2024). "In glioblastoma, TRIM26 could stabilize SOX2 protein, a pluripotency transcription factor, by inhibiting the interaction of SOX2 with its targeting E3 ubiquitin ligase WWP2 to promote the tumorigenicity of glioblastoma stem cells." (PMID 38773612, 2024). "In glioblastoma stem cells isolated from PDX mouse models originally derived from human tumor samples, a subset of super-enhancers at the loci of critical genes, such as CDK6, SOX2, EGFR and BRD4, are shared by the majority of human glioblastoma stem cells." (PMID 38135679, 2023). "Furthermore, KLHDC8A expression positively correlated with the expression of SOX2 and OLIG2 in glioblastoma patients from TCGA and CGGA databases." (PMID 36394953, 2023). "Primary EGFRvIII positive (and SOX2 (SRY-Box Transcription Factor 2) positive or SOX2 negative) glioblastoma cells differentially responded to EGF and TGFβ." (PMID 36292985, 2022). "This makes SOX2 and SFRP2 potential key elements in the regulation of glioblastoma subtypes." (PMID 35701472, 2022). "This work presents SFRP2 and SOX2 as counteracting inducers of gene expression based glioblastoma subtypes, where SFRP2 suppresses SOX2 via non-canonical WNT signaling, KLF4, PDGFRs, and AKT." (PMID 34021259, 2021). "The extensive intra‐ and intertumor heterogeneity of glioblastoma, may account for the inability of surface markers CD133 and Sox2 to characterize GSCs." (PMID 33128777, 2021). "Here SWIM implicated FOSL1 as a putative master regulator of a core of four master neurodevelopmental transcription factors (i.e., SOX2, SALL2, OLIG2, POU3F2), whose induction was demonstrated to be sufficient to reprogram fully differentiated glioblastoma cells into stem-like cells." (PMID 33785068, 2021). "Quantitative confocal analysis of SOX2 immunofluorescence in WWP2 knockdown tumor cells demonstrated a significant increase in SOX2 intensity in individual cell nuclei compared to control tumor cells, suggesting WWP2 is a SOX2 E3 ligase in glioblastoma cells in vivo." (PMID 34732716, 2021). "As opposed to SFRP2, SOX2 expression was significantly lower in mesenchymal TCGA glioblastoma as compared to classical and proneural tumors." (PMID 34021259, 2021).
glioblastoma (continued). "Since no SOX2-targeting E3 ubiquitin ligase has yet been identified in glioblastoma cells, we tested the role of four E3 ubiquitin ligases (CDH1-APC, CUL4A, UBR5, and WWP2) which have been demonstrated to target SOX2 in other cellular contexts through an RNA interference-based approach in GSCs29–32." (PMID 34732716, 2021). "In the context of cancer, and glioblastoma in particular, the functional consequences of altering SOX2 proteostasis have not been well established." (PMID 34732716, 2021). "Regarding previously reported glioblastoma mesenchymal signature transcription factors, SOX2 as opposed to SFRP2, decreased CEBPB and FOSL2 levels consistent with their negative correlation to SOX2 in TCGA glioblastomas." (PMID 34021259, 2021). "Moreover, the PTEN, an inhibitor for the PI3K signaling pathway, represses the expression of stemness and drug resistance markers OCT4, SOX2, NANOG and MDR1 in glioblastoma." (PMID 30944375, 2019). "In cancer stem cells, by the induction of a core set of neurodevelopmental transcription factors (POU3F2, SOX2, SALL2, and OLIG2) that are essential for glioblastoma propagation, differentiated glioblastoma cells can be fully reprogrammed into induced stem-like tumor-propagating cells." (PMID 31375149, 2019). "Four core transcription factors (POU3F2, SOX2, SALL2, and OLIG2) are reported to be essential for glioblastoma propagation and sufficient to fully reprogram differentiated glioblastoma cells into glioblastoma stem cells." (PMID 31375149, 2019). "Taken together, we identified a set of miRNAs that are differentially expressed in GSCs as compared to non-stem glioblastoma cells, several of which correlated with the expression of the stem cell markers Sox-2 and nestin." (PMID 29434344, 2018). "Furthermore, glioblastomas share several membrane markers expressed by NSCs, including CD133, Nestin, SOX2, and GFAP." (PMID 30279357, 2018). "Our findings indicated that PTUPB may target the HMMR/SOX2/ZEB1 signaling axis, inhibiting glioblastoma growth." (PMID 29152086, 2017). "The biological importance of SOX2+ (or NANOG+) HIF-1α+ RNApII-S2P-/low tumor cells was also confirmed by our finding that these cells were found exclusively in glioblastoma tissues but not in grade II–III astrocytoma tissues." (PMID 26799577, 2016). "CD9 silencing in three CD133+ glioblastoma cell lines (NCH644, NCH421k and NCH660h) led to decreased cell proliferation, survival, invasion, and self-renewal ability, and altered expression of the stem-cell markers CD133, nestin and SOX2." (PMID 26573230, 2016). "Moreover, they detected 489 genes whose expression was altered with SOX2 inhibition, including additional SOX family members, cytokines, or BEX members with tumor suppressor activity in glioblastoma." (PMID 27822457, 2016). "In recent years, SOX2 and OCT4 have been identified as biomarkers of CSCs, which regulate proliferation, maintenance of self-renewal capacity, and tumorigenicity, such as in glioblastoma tumor-initiating cells, HNSCCs and esophageal squamous cell carcinomas." (PMID 26202311, 2015). "The expression of Sox2 has been shown to correlate with that of Twist1 in human glioblastoma cells, although direct proof that Sox2 regulates the expression of Twist1 is lacking." (PMID 23815808, 2013). "Since increased invasion and therapy resistance have been observed in cancer stem cells, and ZEB1 is a known regulator of stemness and SOX2 in other solid tissue cancers, we hypothesised that ZEB1 has similar functions in glioblastoma." (PMID 23818228, 2013). "Interestingly, levels of SOX2 are slightly higher in the CD133+ population compared to their CD133− counterparts in DAOY cells, similar to a previous report regarding glioblastoma cells." (PMID 22937156, 2012). "Independent of the percentage of positive cells, SOX2 appeared as strong staining, restricted to the nuclei of glioblastoma cells." (PMID 17375044, 2007).